CBS (cystathionine beta-synthase)
Diseases named in the same sentence as CBS in open-access papers (continued):
Sharing a sentence is not in itself a finding about the gene and the disease.
homocystinuria (continued). "Otherwise, the Cbs gene encodes cystathionine-beta-synthase whose deficiency causes homocystinuria (OMIN236200), a metabolic disorder with intellectual disabilities." (PMID 25706610, 2015). "This level of homocysteine is approximately 3.5-fold higher than that observed in male Cgl null mice and is essentially equivalent to that observed in mouse models of cystathionine beta synthase deficient homocystinuria." (PMID 26276101, 2015). "Our data of CBS mutations causing homocystinuria further confirm the role of CBS in the pathogenesis of homocystinuria." (PMID 26667307, 2015). "Homocystinuria is a very rare autosomal recessive hereditary disease (prevalence 1/200,000) of methionine metabolism due to the deficiency of cystathionine beta-synthase, which is encoded by the gene CBS (21q22.3)." (PMID 25478001, 2014). "Homocystinuria is a rare disorder caused by a defect in methionine metabolism due to inadequate activity of the enzyme cystathionine beta synthase (CBS)." (PMID 25478266, 2014). "In humans, a CBS deficiency results in an elevated level of circulating homocysteine (homocystinuria), which is a risk factor for a number of neurological defects and vascular diseases." (PMID 24146802, 2013). "In humans, genetic mutations invoking CBS deficiency lead to the clinical condition of homocystinuria, not only characterized by severe disorders of brain, but also of eyes, and the musculoskeletal and cardiovascular system." (PMID 21829469, 2011). "Cystathionine beta-synthase (CBS) deficient homocystinuria is an inherited metabolic defect that if untreated typically results in mental retardation, thromboembolism and a range of connective tissue disturbances." (PMID 20638882, 2010). "To gain clinically as well as mechanistically relevant insight into the role of misfolding in CBS deficiency we first selected a series of naturally occurring CBS mutations for further laboratory studies." (PMID 20506325, 2010). "We examined properties of a series of 27 mutant variants, which together represent 70% of known alleles observed in patients with homocystinuria due to CBS deficiency." (PMID 20506325, 2010). "A frequent mutation in the CBS gene in Caucasian patients, c.919G>A (p.G307S), is one of the most common causes of homocystinuria in patients of Celtic origin and this mutation accounted for 71% of alleles in Irish homocystinuria patients." (PMID 19657388, 2009). "In humans, mutations in CBS cause homocystinuria, associated with vascular disease, with >130 CBS mutations identified in patients." (PMID 19956742, 2009). "Disturbances in this process can lead to an increased cellular Hcy level and the most common type of inherited homocystinuria in the human is caused by a deficiency in CBS." (PMID 19657388, 2009). "Homocystinuria caused by cystathionine beta synthase (CBS) deficiency is a rare autosomal recessive disorder of sulfur amino acid metabolism." (PMID 18950795, 2009). "The experiments in this work were motivated by the apparent paradox presented by the p.S466L mutation: How can a CBS enzyme that is enzymatically active in vitro cause homocystinuria in vivo?" (PMID 18454451, 2008). "Mutations in the CBS gene cause clinical CBS deficiency (homocystinuria), a metabolic disorder characterized by extreme elevations in plasma total homocysteine (tHcy)." (PMID 18454451, 2008). "Missense mutations in the cystathionine β-synthase (CBS) gene are the most common cause of clinical homocystinuria in humans." (PMID 18454451, 2008). "Our results show that p.S466L causes homocystinuria by affecting both the steady state level of CBS protein and by reducing the efficiency of the enzyme in vivo." (PMID 18454451, 2008). "Homozygosity or compound heterozygosity for the c.833T>C transition (p.I278T) in the cystathionine beta-synthase (CBS) gene represents the most common cause of pyridoxine-responsive homocystinuria in Western Eurasians." (PMID 17072863, 2007).
homocystinuria (continued). "CBS deficiency, or classic homocystinuria, is caused by mutations in the CBS gene and is the most common inherited disorder of sulfur metabolism." (PMID 17540596, 2007). "On the other hand, gross deficiency in CBS activity is associated with homocystinuria, an inborn recessive metabolic disorder." (PMID 16375773, 2005). "Similarly, homocystinuria, due to mutations in the CBS gene encoding cystathionine β-synthase, results in impaired homocysteine metabolism and secondary vitamin B6 deficiency." (PMID 41149778, 2025). "We identified a patient with SCAD (case 10_241) with a CBS variant, a gene that encodes for cystathionine β‐synthase and is typically associated with autosomal recessive phenotypes including a Marfan‐like syndrome and homocystinuria." (PMID 40194966, 2025). "Cystathionine β‐synthase (CBS) deficiency (classical homocystinuria) has a wide range of severity." (PMID 40095936, 2025). "Moreover, the study identified three patients with compound heterozygous CBS mutations causing homocystinurias, compound heterozygous DPYD mutations causing DPD deficiency, and homozygous GALC mutations causing Krabbe Disease, respectively." (PMID 37237429, 2023). "Here, we will discuss the pathophysiology, diagnosis, clinical features and management of three autosomal recessive disorders of amino acid metabolism: phenylketonuria (PKU), lysinuric protein intolerance (LPI) and homocystinuria due to cystathionine β-synthase (CBS) deficiency." (PMID 37994477, 2023). "Finally, numerous missing mutations that disrupt the structure of CBS in humans result in classical homocystinuria due to cystathionine β-synthase (CBS) deficiency." (PMID 35740876, 2022). "In addition, human mutations of CBS genes result in homocystinuria accompanied by strong cognitive impairments and many other abnormalities." (PMID 35740876, 2022). "One of these putative novel biomarkers for CBS deficiency, 5′‐methylthioadenosine, is currently validated in CBS‐deficiency patients using orthogonal methods and was previously reported to be found in a mouse model of CBS–homocystinuria." (PMID 35546254, 2022). "The two pathways ranking higher than biomarker pathways are hypothesised to be unrelated to CBS deficiency, but further work on samples from other CBS patients is required to confirm this with certainty." (PMID 35546254, 2022). "We had previously reported that Met accumulated highly in the CSF of 2-week-old CBS-deficient mice (488 μM compared to 24 μM in wild-type mice), an animal model of homocystinuria/homocysteinemia, and that adult CBS-deficient mice displayed cerebellar malformation and impaired learning ability." (PMID 35055113, 2022). "Although the prevalence of c.833T>C is likely less among the Asian population, but it is the most prevalent mutation worldwide in the CBS gene related to homocystinuria, thus, it is important to find out the presence and prevalence of this mutation in Sri Lanka." (PMID 36512268, 2022). "CBS deficiency is treatable: pyridoxal 5 ́-phosphate is a coenzyme for CBS and patients with milder forms of CBS deficiency usually respond to treatment (in terms of lowering tHcy to target levels or even close to the normal range) with pharmacological doses of its precursor pyridoxine." (PMID 33691747, 2021). "Classical homocystinuria is caused by cystathionine beta-synthase (CBS) deficiency." (PMID 33691747, 2021). "In this study a homozygous missense change (NM_000071.3: c.253G>A; p.Gly85Arg) was identified through whole exome sequencing in the catalytic domain of the CBS gene causing classical homocystinuria in three affected siblings of a Pakistani consanguineous family." (PMID 34342182, 2021). "Therefore, classical homocystinuria, due to a deficiency in CBS activity, is the most common inborn error of sulfur amino acid metabolism." (PMID 32245022, 2020). "However, this stand-alone field of CBS mutations and homocystinuria was only briefly discussed in the current article." (PMID 32365821, 2020).
homocystinuria (continued). "CBS mutations and clinical phenotypes of homocystinuria in Arab countries." (PMID 32245022, 2020). "Homocystinuria is a monogenic disease caused by a deficiency in the activity of the CBS enzyme." (PMID 32245022, 2020). "Since the identification of the first disease-causing CBS variants, several hundred alleles have been identified in homozygous or compound-heterozygous homocystinuria patients, many of which have been further genetically and biochemically characterized, yielding ~ 200 annotated pathogenic variants." (PMID 32000841, 2020). "Tall stature may also be associated with the triple X (47XXX), fragile X, and Klinefelter (47XXY) syndromes, homocystinuria due to mutations in CBS encoding cystathionine beta-synthase, and inactivating variants of ER encoding the estrogen receptor." (PMID 32300792, 2020). "In addition, eight novel mutations in CBS were identified in Chinese patients with classical homocystinuria." (PMID 32245022, 2020). "Therefore, the biochemical fingerprint of CBS deficiency or classical homocystinuria is elevated Hcy in the presence of high Met and often low cystathionine." (PMID 33179601, 2020). "Homocysteinemia could be caused by several genetic factors, including deficiencies of cystathionine β-synthase (CBS) (homocystinuria; MIM 236200), 5,10-methylenetetrahydrofolate reductase (MIM 236250), or methionine synthase (MIM 250940)." (PMID 31319489, 2019). "This could explain the higher median age of diagnosis, and the delay between the onset of symptoms and diagnosis of homocystinuria in CBS-deficient B6 responders in the present study." (PMID 30871635, 2019). "Homocystinuria due to congenital deficiency of the CBS gene causes hyperhomocysteinemia." (PMID 30646578, 2019). "Deregulation of CBS and the associated alterations in Hcy and/or H2S levels leads to a wide range of pathological disturbances in the cardiovascular, immune, and central nervous systems and contributes to disease development, such as CBS-deficient homocystinuria (CBSDH)." (PMID 30050925, 2018). "The enhanced affinity for inhibitory gaseous ligands documented here may represent a new pathogenic mechanism at the basis of CBS-related diseases, like classical homocystinuria." (PMID 28421128, 2017). "This may represent a more general mechanism of pathogenesis in classical homocystinuria, if other pathogenic CBS mutations will be demonstrated to lead to enhanced CO affinity, as shown for CBS p.P49L in the present study." (PMID 28421128, 2017). "In human, CBS recessive mutation deficiency leads to homocystinuria (OMIM 236200)." (PMID 28266534, 2017). "The obtained functional and structural data are discussed in light of the proposal that in pathogenic variants of human CBS increased reactivity towards exogenous ligands, such as CO, represents a further molecular mechanism at the basis of classical homocystinuria." (PMID 28421128, 2017). "This study expands the mutation spectrum of CBS resulting in homocystinuria, which could provide insights into the pre-symptomatic molecular diagnosis, the management of homocystinuric patients, and the genetic counseling of families in Chinese." (PMID 26667307, 2015). "Defects in this gene can cause CBS deficiency, which can lead to homocystinuria." (PMID 26667307, 2015). "This study was aimed to detect the mutations in CBS in a Han Chinese family with homocystinuria." (PMID 26667307, 2015). "This study provides a mutation spectrum of CBS resulting in homocystinuriain a Chinese population, which may shed light on the molecular pathogenesis and clinical diagnosis of CBS-associated homocystinuria." (PMID 26667307, 2015). "Additionally, CBS mutations are associated with homocystinuria, iridodonesis and agitated motion of the iris [MIM 236200]." (PMID 24651765, 2014).
homocystinuria (continued). "Notably, CBS deficiency causes increased plasma methionine levels and decreased cysteine levels which in turn are known to correlate with homocystinuria, cardiovascular disease and hepatocellular carcinoma." (PMID 23152928, 2012). "In summary, our results show that topology of mutations predicts in part the behavior of mutant CBS, and that misfolding may be an important and frequent pathogenic mechanism in CBS deficiency." (PMID 20506325, 2010). "Insufficiency in CBS activity may lead to hyperhomocysteinemia and a gross deficiency in CBS activity is associated with homocystinuria, an inborn recessive metabolic disorder." (PMID 21119889, 2010). "Previously, we have shown using a yeast system that enzymatic function could be restored to I278T cystathionine β-synthase (CBS), a cause of homocystinuria, by treatments that affect the intracellular chaperone environment." (PMID 20066033, 2010). "Previously we had developed a mouse model for homocystinuria caused by I278T CBS (Tg-I278T Cbs−/−)." (PMID 20066033, 2010). "The surprisingly high frequency of the c.1105C>T allele among Norwegian newborns suggests that this CBS mutation may be the most common cause of homocystinuria in North Europeans." (PMID 18950795, 2009). "The vast majority of patients with clinical homocystinuria have missense mutations in the CBS gene." (PMID 17540596, 2007). "Cystathionine β-synthase (CBS) mediates conversion of homocysteine to cystathionine and deficiency in enzyme activity may lead to hyperhomocysteinemia/homocystinuria, which are often associated with mental retardation (MR)." (PMID 16375773, 2005). "The frequency differences in these mutations in the Chinese population suggest that there may be racial differences in the distribution of CBS gene mutations, and it is therefore necessary to screen for mutations in a larger group of patients with homocystinuria." (PMID 40299504, 2025). "Furthermore, chemical chaperones have been demonstrated to enhance the activity of mutated PHA, mutated cystathionine beta-synthase known to be associated with homocystinuria, and mutated branched-chain alpha-ketoacid decarboxylase which is associated with maple syrup urine disease." (PMID 34502079, 2021). "Plasma elevation of total homocysteine (tHcy) or hyperhomocysteinemia may result from congenital deficiency of cystathionine β-synthase (CBS) leading to homocystinuria, or more frequently from polymorphisms of the cystathionine γ lyase (CTH) gene (OMIM *607657; EC 4.4.1.1)." (PMID 30646578, 2019). "In several countries methionine is used as a marker in newborn screening to detect patients with homocystinuria due to CBS deficiency, although the sensitivity and the specificity for detecting CBS deficiency is poor, in particular for B6-responsive CBS deficient patients." (PMID 27671891, 2017). "CBS mutations could lead to the disruption of enzyme activity which consequently results in increased levels of homocysteine, a potentially toxic amino acid responsible for patients with homocystinuria." (PMID 26667307, 2015). "The population frequency of patients with clinically ascertained and biochemically confirmed CBS deficiency varied considerably between countries, averaging ∼1 out of 1,500,000 inhabitants in Europe and yielding an estimated population frequency of pathogenic CBS alleles of 0.82 × 10−3." (PMID 17072863, 2007). "Through in vitro minigene experiments, we analyzed the effects of splice mutations on the level of CBS transcripts and protein function and further confirmed the role of CBS in the pathogenesis of homocystinuria." (PMID 40299504, 2025).
homocystinuria (continued). "The CBS and PADI3 genes are associated with homocystinuria (MIM# 236200) and uncombable hair syndrome (MIM# 191480) respectively." (PMID 38584274, 2024). "Homocystinuria (CBS gene defect) is characterized by ectopia lentis, myopia, tall stature, long limbs, scoliosis, pectus excavatum, thromboembolism, and developmental delay or mental retardation." (PMID 39421111, 2024). "As our goal was to study the effect of moderate HHcy, we used a genetic knockdown (KD) approach in our model generation instead of a CBS knockout (KO) model which mimic Homocystinuria, a severe form of HHcy." (PMID 38334606, 2024). "Regarding biochemical analysis, classic homocystinuria is characterized by elevated plasma Hcy and methionine, as well as decreased cysteine, as these are distal to the impaired CBS." (PMID 37994477, 2023). "According to the Human Gene Mutation Database, more than 200 pathogenic mutations in the CBS gene and more than 40 in the MTHFR gene have been identified worldwide related to homocystinuria." (PMID 36512268, 2022). "Lack of CBS activity results in classical homocystinuria, an inborn error of metabolism characterized by highly elevated plasma and tissue concentrations of Hcy." (PMID 35864237, 2022). "This study was mainly focused on detecting the selected variants of CBS and MTHFR genes and their association with homocystinuria." (PMID 36512268, 2022). "Homocystinuria is a rare autosomal recessive metabolic disorder due to a defect in the cystathionine β-synthase (CBS) that leads to high homocysteine plasma levels." (PMID 33824770, 2021). "The finding of plasmatic CBS enzymatic activity has been proposed as a tool for the diagnosis of patients with classic homocystinuria." (PMID 34356298, 2021). "Through WES, a missense SNP of the CBS gene responsible for classical homocystinuria was revealed, which developed CC secondarily in the patients." (PMID 34342182, 2021). "Homocystinuria due to cystathionine beta-synthase (CBS) deficiency, also known as classical homocystinuria (OMIM.org #236200), is a rare recessive inherited amino acid metabolism disorder that involves the pathway for cystathionine synthesis." (PMID 33985475, 2021). "Severe hyperhomocysteinemia is a characteristic biochemical feature of classical homocystinuria (HCU), a rare autosomal recessive inborn error of sulfur amino acid metabolism caused by a deficiency in cystathionine beta-synthase (CBS) activity." (PMID 32722248, 2020). "Classical homocystinuria (HCU), caused by mutations in the cystathionine beta synthase (CBS) gene, is an inherited genetic disorder in which the body is unable to metabolize the amino acid homocysteine (Hcy), a key molecule in several metabolic processes." (PMID 32143624, 2020). "In the present study, we report the clinical and biochemical profiles and the spectrum of CBS gene variations in North Indian children presenting with classical homocystinuria." (PMID 33057012, 2020). "Based on the hallmark clinical features, family history, and/or biochemical clues for classical homocystinuria, 16 children below the age of 18 years were evaluated by Sanger sequencing of the coding exons of CBS gene with flanking intronic regions." (PMID 33057012, 2020). "CBS is used to confirm homocystinuria when high levels of methionine are detected by mass spectrometry." (PMID 32944285, 2020). "It is known that the disturbance in the CBS/CSE system results in homocystinuria and the development of inflammation in the excretory system in mammals." (PMID 32769010, 2020). "The most common cause of genetic homocystinuria is cystathionine beta‐synthase (CBS) deficiency or classical homocystinuria (HCU) (OMIM #236200), which is an autosomal recessive disease caused by biallelic pathogenic variations in CBS gene." (PMID 32232970, 2020).